HSF1 (heat shock transcription factor 1)
Diseases named in the same sentence as HSF1 in open-access papers (continued):
Sharing a sentence is not in itself a finding about the gene and the disease.
cancer (continued). "Recent research showed that HSF1 promoted tumorigenesis via a variety of ways, including maintaining proteostasis, reprogramming metabolism, facilitating cancer cell proliferation and migration, repairing the genome, preventing cell death, and altering the TME." (PMID 34239690, 2021). "Recent studies have found that HSF1 may be related to tumorigenesis, and is activated in the process of canceration, and is closely related to the survival and proliferation of cancer cells." (PMID 34539881, 2021). "It was shown that reduction in HSF1 levels and/or activity is suppressive to cancer cell growth." (PMID 34200371, 2021). "Thus, because of its central role in cancer biology, HSF1 is an interesting therapeutic target in the treatment of OS." (PMID 33808130, 2021). "Therefore, it is particularly important to deeply examine the regulatory functions and molecular mechanisms of HSF1 in a pan-cancer dataset to provide new directions and strategies for the clinical treatment of cancer." (PMID 34239690, 2021). "It is well-known that HSF1 in cancer cells exerts functions unrelated to the heat shock response, so the regulation of HSF1 in the context of EMT may or may not have a direct effect on thermotolerance." (PMID 34768807, 2021). "Our pan-cancer analysis provides a deep understanding of the functions of HSF1 in oncogenesis in different cancers and identifies strategies that may be used to promote collaborative activities in the context of immunotherapy." (PMID 34239690, 2021). "The present study first comprehensively examined the expression of HSF1 in a pan-cancer dataset." (PMID 34239690, 2021). "To better understand the contexts that drive cellular dependence on HSF1, we compared the transcriptome, metabolome, and proteome for cells highly dependent on HSF1 (>75th percentile essentiality) as compared with relatively HSF1-independent cell lines (<25th percentile) across major cancer subsets." (PMID 33328249, 2021). "HSF1 was shown to be activated in hypoxia-stressed cancer cells." (PMID 33806538, 2021). "It is generally assumed that HSF1 governs many aspects of cancer cell growth and metabolism." (PMID 34200371, 2021). "Therefore, it is a common knowledge that HSF1 is the king regulator of HSPs expression and the major mediator of their induction in cancer." (PMID 34198675, 2021). "Increased phosphorylation of S303, S307, and S363 in HSF1 was observed in some cancers." (PMID 34239690, 2021). "Finally, based on different types of cancer, we consider the advantage of targeting heat shock factor 1 (HSF1), the major transcriptional regulator of HSPs in OS." (PMID 33808130, 2021). "In addition, numerous reports demonstrated that the expression of HSF1 was notably elevated in various human cancers." (PMID 34064083, 2021). "Thus, targeting DYRK2 can significantly affect proteostasis via perturbation of both HSF1 and 26S proteasome activity leading to cancer cell death." (PMID 33376136, 2021). "Genetic studies in cancer cells and normal cells demonstrated that HSF1 orchestrated the transcriptional regulation of genes aside from heat shock genes, which suggests that it participates in tumorigenesis by driving various unique signaling pathways and oncogenesis-related genes." (PMID 34239690, 2021). "A broad spectrum of cancers exhibit high levels of nuclear and active HSF1, suggesting that HSF1 might exert oncogenic effects and act as a key facilitator of diverse cancers." (PMID 34922589, 2021). "In addition, erastin has been reported to stimulate HSF1‐dependent HSPB1 expression in cancer cells to confer protection against ferroptosis." (PMID 33675143, 2021). "In addition to the classical role of HSF1 in protein homeostasis, HSF1 transcriptionally regulates a distinct pathway that supports malignant transformation and cancer cell survival and proliferation." (PMID 34203709, 2021). "Targeting HSF1 as a therapy in cancers is indeed a growing field." (PMID 34439354, 2021).
cancer (continued). "Our results suggest that HSF1 activation can attenuate the sensitivity of cancer cells to chemotherapy drugs and that the inhibition of HSF1 may be a novel target for developing a sensitization strategy to NSCLC chemotherapy in the clinic." (PMID 33675143, 2021). "We evaluated the potential correlations between the HSF1 expression and tumor mutational burden (TMB), microsatellite instability (MSI), DNA methylation, immune infiltration levels, and various immune-related genes across multiple cancer types." (PMID 34239690, 2021). "This problem may be solved by combining the HSP90 activity inhibitors with inhibitors of HSF1 activation, as was proposed for enhancing the radiosensitization of cancer cells." (PMID 33806538, 2021). "As the master controller of the heat shock response (HSR) to proteotoxic stresses, HSF1 is crucial in cancers because it enables cancerous cells to copy oncogenic stress or drastic conditions by inducing the expression of cytoprotective chaperone proteins, such as HSP70, HSP40, and HSP27." (PMID 33675143, 2021). "It has been confirmed that HSF1 is highly expressed in various rapidly proliferating carcinomas." (PMID 34064083, 2021). "However, comparing the transcriptomes of tumor cells with those of heat-shocked cells indicated marked differences in the transcriptional properties of the constitutively activated HSF1 found in advanced cancer." (PMID 32331382, 2020). "HSF1 and its gene targets are essential for tumorigenesis across several experimental tumor models, and facilitate metastatic and resistant properties within cancer cells." (PMID 32331382, 2020). "As the most immediate and direct activator of HSP synthesis, it was then hypothesized that HSF1 might be switched on during the development of cancer, and in fact, this was subsequently observed in studies in tissue culture." (PMID 32331382, 2020). "Apart from DNA repair, HSF1 indirectly modulates the expression of β-catenin, a pivotal component of the Wnt signaling pathway that affects numerous aspects in tumorigenesis, such as immunity and cancer stem cell maintenance." (PMID 32408596, 2020). "One could envisage a role for HSF1 in amplifying the rate of elongation in cancer through transcription of HSP90 and triggering of this mechanism." (PMID 32331382, 2020). "In addition, HSP-independent mechanisms are also reportedly involved in HSF1-regulated resistance of cancer cells to chemotherapeutics." (PMID 32457290, 2020). "It is believed that the lack of full success in the treatment of cancer using this type of Hsp90 inhibitors may be due to activation of HSF1 and overexpression of Hsp70 in GA-treated cells, and in this way cancer growth is supported." (PMID 32722570, 2020). "Hsf1 null mice are highly resistant to cancer in the AOM-DSS model." (PMID 33288768, 2020). "Activation of HSF1-dependent stress response, a cytoprotective mechanism, may greatly influence the development of an adaptive and protective phenotype in cancer cells subjected to anticancer agents." (PMID 32457290, 2020). "Here, we investigated the mechanism for cancer-specific overexpression of HSF1." (PMID 32838807, 2020). "HSF1 may coordinate resistant cancer cell properties through chromatin organization in cooperation with HDACs or other DNA-modifying complexes, such as MTA1, each of which have also been linked to resistance to cytotoxic compounds." (PMID 32331382, 2020).
cancer (continued). "In this context, it can be hypothesized that overexpression of SRSF3 might confer resistance to cancer cells upon various stresses through the promotion of nuclear location of HSF1 in cooperation with BIS." (PMID 33086735, 2020). "The frequent amplification of HSF1 mRNA expression across many cancer types would provide higher levels of the target for any delivered homologous RNAi molecule compared to normal tissue, and thereby possibly increase the chances of a greater fold reduction of HSF1 expression." (PMID 32331382, 2020). "However, compared to other oncogenic factors, the structure of HSF1 appears to be maintained with high fidelity in a range of cancers, perhaps suggesting the need for intact HSF1 in transformation and tumor progression." (PMID 32331382, 2020). "The anti-cancer effects of HDACis, raise a possibility that they could, most probably indirectly, increase acetylation of HSF1, which in turn has been shown to stimulate de-activation of HSF1 and thereby attenuate the heat shock response." (PMID 32408596, 2020). "The upregulation of HLNC1 in HCC through HSF1 may partially enhance cancer progression via decreasing the level of USP49 mRNA and USP49 proteins were consistently downregulated." (PMID 32691951, 2020). "In cancer, abnormal modification of HSPs could alter interactions with and regulation of HSF1, while an aberrant HSF1 modification states may drive malignant growth." (PMID 32331382, 2020). "In 2007, two groundbreaking studies demonstrated the importance of HSF1 in cancer." (PMID 32408596, 2020). "The first study was published in 2012 by Mendillo and colleagues, who showed that HSF1 drives a cancer-specific transcriptional program in different types of tumors, which supports numerous oncogenic processes, such as cell-cycle regulation, metabolism, and adhesion." (PMID 32408596, 2020). "The simplest and most immediate hypothesis for HSF1 activation in cancer is that cells undergo proteotoxic stress during tumorigenesis, in a milder recapitulation of the heat shock response." (PMID 32331382, 2020). "HSF1 is an emerging cancer therapeutic target in recent research." (PMID 32110802, 2020). "The HSF1–MTA1 interaction may be a mechanism by which HSF1 epigenetically reprograms the genome to drive a cancer-specific transcriptional program." (PMID 32331382, 2020). "This study revealed HSF1 as a novel downstream target for β-catenin to promote cancer development, indicating that HSF1-targeting molecules could be tried for the intervention of human cancer driven by activated WNT/β-catenin signaling." (PMID 32838807, 2020). "Indeed, we observed high nuclear HSF1 staining in both cancer cells and fibroblasts in these patients compared to control, suggesting that HSF1 is activated in human CAC." (PMID 33288768, 2020). "However, activation of HSF1 also promotes HSP expression in cancer cells that together with other HSF1 activities facilitate tumor cell survival, resistance, and enables malignant cell growth." (PMID 32331382, 2020). "Severe aneuploidy, however, may lead to the depletion of HSF1 and could compromise HSP90 chaperone activity, suggesting that certain cancer cells may be susceptible to therapies that further disrupt the protein-folding capacity." (PMID 32331382, 2020). "In a variety of human carcinomas, HSF1 is activated in CAFs." (PMID 33288768, 2020). "HSP90 transcription is mediated by heat shock factor 1 (HSF1), the master regulator of the heat shock response, basally activated in cancer cells to cope with proteotoxic stress due to aneuploidy, oxidative stress and reactive oxygen species (ROS), hypoxia and acidosis." (PMID 31052524, 2019). "Moreover, overexpression of HSP72 (HSP70) induced by bortezomib was found to limit the anti-cancer effects of bortezomib, and combination therapy with HSF1 inhibitor was effective in enhancing bortezomib-mediated cancer cell death." (PMID 31878360, 2019).
cancer (continued). "Accordingly, HSF1 has been implicated in several fundamental biological processes being independent of the HSR, including metabolism, gametogenesis, development, and ageing, as well as in various pathologies, especially neurodegenerative disorders and cancer." (PMID 31752429, 2019). "While the previous view was that HSF1’s main impact on tumor biology occurs indirectly through the regulation of HSP90 and HSP70, recent research has shown that HSF1 may play a more direct role in altering the transcriptome of cancer cells." (PMID 30634515, 2019). "Furthermore, HSF1 functions to allow cancer cell formation and progression by inducing genomic instability and stabilizing mitotic spindle organization through regulation of Cyclin D, p21, and p27 during mitosis." (PMID 31878360, 2019). "Indeed, no less than 5000 publications were found for 16 popular genes including HSF1 in 8q24.3, of which 800 publications related to cancer field, mainly because those genes were found overexpressed in cancer." (PMID 31699156, 2019). "HSF1 has been associated to aggressive CAF behaviours by its ability to drive a transcriptional programme that supports the malignant potential of cancer in a non-cell-autonomous way6." (PMID 30631061, 2019). "Accumulating evidence reveals however that HSF1 participates in several other physiological and pathological processes such as differentiation, immune response, and multidrug resistance, as well as in ageing, neurodegenerative demise, and cancer." (PMID 31752429, 2019). "After screening for low-toxic HSF1 inhibitors with the help of heat-shock-element-luciferase reporter assays we identified cardioglycoside CL-43 as a drug which was able to reduce the growth rate of cancer cells." (PMID 31652993, 2019). "Since mammalian HSF1 has been shown to support progression of highly malignant cancers, it is crucial to develop strategies that can selectively modulate the activity of this transcription factor to promote longevity in animals without producing undesired outcomes." (PMID 30894454, 2019). "Heat shock factor 1 (HSF1) is a canonical transcription factor that mediates cell stress and induces the production of HSPs, although several additional transcription factors recently identified can be involved in cancer progression and resistance." (PMID 31533245, 2019). "Furthermore, it has been reported that treatment of cancer cells with HSP inhibitors or proteasome inhibitors results in HSF1 activation and compensatory induction of HSPs thereby reducing the antitumor activity of such inhibitors." (PMID 31540420, 2019). "The presented results suggest that HSF1 activated by estrogen could support cancer cells’ growth independently of its cytoprotective function mediated by chaperones." (PMID 31614463, 2019). "From the phenotypic screen targeting HSF1 heat shock pathway with a chemically diversified library of over 100,000 compounds, PW3405 has been identified to inhibit phosphorylation and activity of HSF1 and suggested to inhibit cancer cell viability in a broad range of tumors in vitro." (PMID 31878360, 2019). "Intriguingly, overexpression of HSF1 cancer signature gene clusters at the end of chromosome 8q." (PMID 31699156, 2019). "In addition to its role in HSR, HSF-1 has major functions in other biological processes such as development, reproduction, metabolism and cancer." (PMID 30894454, 2019). "Aberrant expression and activation of HSF1 is involved in cancer progression and drug resistance." (PMID 30444038, 2019).
cancer (continued). "In conclusion, the combinations of direct (KRIBB11) or indirect (triptolide, kinase inhibitors) HSF1 inhibitors with proteotoxic factors like proteasome inhibitors or traditional anti-cancer drugs, such as cytostatics, can overcome the resistance of tumor cells which is based on chaperones." (PMID 31652993, 2019). "Hence, phosphorylation and activation of HSF-1 followed by protection of cancer cells occurs invariably during chemotherapy and radiation." (PMID 29682483, 2018). "With Hsf1 and Hsp90 as core hubs of cellular circuitry in diverse cells types, there has been a growing appreciation of the therapeutic potential of targeting these regulators in treating cancer, neurodegenerative disorders, and infectious disease." (PMID 29590106, 2018). "The HSF1 expression was high in patients with all histological grades of cancer." (PMID 29494616, 2018). "In addition to supplying high levels of chaperones to cancer cells, Hsf1 takes on specialized transcriptional roles to support malignant growth, and its activity is associated with poor prognosis in a range of human cancers." (PMID 29393852, 2018). "Therefore, we assessed the endogenous stress response of cancer cells by measuring HSF1 activity in correlation with sensitivity to Hsp90 inhibitors." (PMID 30138434, 2018). "As HSF-1 is important for both cancer and normal cells under stress conditions, systemic inhibition of HSF-1 could exert not only anticancer activity but also toxicity to normal cells." (PMID 29682483, 2018). "However, it is not well established that the beneficial effect of these compounds are due to inhibition of HSF-1 in cancer cells." (PMID 29682483, 2018). "Absence of HSF1 reduces proliferation and survival of human cancer cell lines, and protects mice from mutation- or carcinogen-driven tumors." (PMID 30131848, 2018). "HSF1 is an evolutionarily highly conserved transcription factor essential for cancer cell survival." (PMID 30356024, 2018). "HSF1 is a potentially better target for cancer therapy than HSP90 and several other HSPs." (PMID 30356024, 2018). "Hsf1 has been shown to play pro-cancer roles both in tumor cells and the supporting stroma." (PMID 29393852, 2018). "As our understanding of biological pathways regulated by HSF1 in supporting cancers deepens, such as the role of the PIKK family, CDK9, and Pirin in the inhibition of the HSF1 stress pathway, identification of new chemotypes as potential candidate for cancer therapy will be easier." (PMID 30356024, 2018). "This paradox further strengthens our perception that highly specific HSF-1 inhibitors are essential, not only to use as a cancer therapeutic but it is also required to understand HSF-1-dependent mechanistic pathways of these nutraceuticals in laboratory studies." (PMID 29682483, 2018). "Therefore, identifying a suitable inhibitor for successful inhibition of HSF-1 to assist/enhance treatment outcome of human cancer should come from the hands of phytochemists, who can isolate the natural compounds and modify the efficacy of these inhibitors." (PMID 29682483, 2018). "Previous studies have reported that HSF1 could function as a potential tumour oncogene in different cancers." (PMID 30326922, 2018). "As HSP70 directly represses HSF1 through binding its transcription activation domain, trapping HSP70 on HSF1 could prevent increased expression of HSPs in proliferating cancer cells." (PMID 30220976, 2018). "It is not currently known how the HSF-1 is involved in the increased production of anticancer agents in these stressed plants, and whether inhibiting HSF-1 activity in these plants will reduce the contents of these cancer-inhibiting compounds." (PMID 29682483, 2018). "Overexpression of HSF1 has been reported in several cancer studies." (PMID 29494616, 2018). "It appears that cancer cells may hijack HSF1 functions and its transcriptional activity to promote survival, growth and metastatic propensity." (PMID 30131848, 2018).